ESR1 (estrogen receptor 1)
Diseases named in the same sentence as ESR1 in open-access papers (continued):
Sharing a sentence is not in itself a finding about the gene and the disease.
tumor (continued). "For example, the gene ESR1 (estrogen receptor 1), which was identified as a key driver of tumor growth in our model, showed consistent expression patterns across all three datasets." (PMID 40379718, 2025). "Contrary to expectations, ESR1 transcriptional levels were significantly lower in tumor tissues, yet paradoxically, high ESR1 expression correlated with improved patient survival." (PMID 40342082, 2025). "For instance, higher mRNA expression levels of MKI67, ERBB2, and ESR1 have been positively correlated with higher tumor stages and grades, suggesting their potential utility in clinical practice." (PMID 40948378, 2025). "Implementing this approach requires regular biomarker monitoring, such as ESR1 detection in circulating tumor DNA, along with the availability of effective therapies to counteract the identified resistance pathways." (PMID 41226406, 2025). "Specifically, MKI67 expression showed a strong correlation with tumor grade, while ESR1 and ERBB2 also demonstrated significant differences between various grades and stages." (PMID 40948378, 2025). "The results demonstrated that the addition of E2 suppressed the tumor formation ability of cancer stem cells, and after interfering with ESR1, the inhibitory effect of E2 became less evident." (PMID 40342082, 2025). "We therefore focused on the functions of Smyd3 and Esr1 in gene expression, tumor initiation and progression." (PMID 40157910, 2025). "UMAP distribution showed that AKT1 and ESR1 were primarily expressed in tumor cells, SRC and IL6 were concentrated in the Myeloid subpopulation, while MTOR and HIF1A exhibited a broader distribution across multiple cell types." (PMID 40746726, 2025). "It was observed that the high-expression group of AURKA exhibited higher tumor purity, whereas the high-expression groups of CYP1A2 and ESR1 were associated with lower tumor purity." (PMID 40864066, 2025). "GREB1-rearranged UTROSCTs showed significantly greater tumor diameter than did ESR1-rearranged UTROSCTs (7.2 ± 4.3 vs. 3.8 ± 3.3 cm; p = 0.002) and were less likely to display a submucosal exophytic growth (23.1% vs. 60%; p = 0.005)." (PMID 40150134, 2025). "One of the most extensively studied miRNAs in this context is miR-206, which acts as a tumor suppressor and has been shown to directly target ESR1, leading to post-transcriptional downregulation of ERα." (PMID 41283333, 2025). "We have previously published on enhanced cell-cell adhesion networks in ESR1 point mutant models that translated to increased circulating tumor cell clusters in patients with metastatic, endocrine-resistant disease." (PMID 39207954, 2024). "Compared to the control group after 48 h of treatment with TGT, the expression of genes JUN, TYMS, HSP90AA1, HDAC1, CDK1, and ESR1 was downregulated, which showed inhibitory effect on tumor cell proliferation." (PMID 38297292, 2024). "They observed that VT02956 inhibits ESR1 expression by targeting the Hippo pathway, resulting in the growth of ER+ BC cells and patient-derived tumor organoids, with little cytotoxicity in other cells." (PMID 38344206, 2024). "In PDX models bearing the ESR1 Y537S mutant, palazestrant inhibits tumor growth at a 3 mg/kg dose and enhances tumor shrinkage at higher doses or combined with CDK4/6 inhibitors." (PMID 39767607, 2024). "In contrast, luminal A/B tumor cells and LM cells showed high accessibility for the ER ESR1, as well as forkhead proteins, including FOXA2 and FOXP1, GATA3 and other GATA-box TFs, and HNF1A." (PMID 39478117, 2024). "They reported the presence of ESR1 mutations in 9 out of 60 (15%) FFPE samples and in 11 out of 80 (13.8%) circulating tumor DNA (ctDNA) samples from advanced and metastatic ovarian cancer patients." (PMID 38791941, 2024). "To obtain information on the reduction of tumor aggressiveness in stratification by ESR1, we performed a DAVID_GO analysis (a functional annotation clustering tool) to search for the pathways co-upregulated with this gene in GBM." (PMID 38411438, 2024).
tumor (continued). "The findings suggest that the expression of GPER1 and ESR1 RNA in tumor cells is probably regulated by DNA methylation." (PMID 38666956, 2024). "To characterize the effects of T6I-29 on tumor growth and to determine the best mode of delivery, we used an ectopic murine Y537S ESR1 MCF7 xenograft model and treated with different doses of T6I-29-1A." (PMID 38978585, 2024). "Pilot in vivo studies showed a significant inhibition of tumor growth when Y537S ESR1 xenograft tumors were treated with T6I-29-1A, with more significant anti-tumoral effects observed in the I.P. pilot study." (PMID 38978585, 2024). "A phase 2 clinical study found that H3B-6545 had a tolerable safety profile and anti-tumor effectiveness in previously treated ER+ and HER2-metastatic BC patients, including those with ESR1 mutations." (PMID 39274207, 2024). "Specifically, our investigation revealed a notable upregulation of the ESR1 gene in tumor tissue, correlating with unfavorable prognoses, as depicted in the OS graph." (PMID 38732206, 2024). "Only very recently has a similar association been reported between activating mutations in the RTK/MAPK pathway or ESR1 and the PAM50 molecular subtype of a tumor in HR + /HER2- MBC29." (PMID 38503755, 2024). "As the estimation of EERES and ESR1 expression relies on bulk tumor tissue, the proportion of cancer cell and stroma would affect the accuracy of the estimation." (PMID 38582811, 2024). "Uterine tumors resembling ovarian sex cord tumors (UTROSCT) represent another tumor with recently characterized recurrent fusion genes involving ESR1, GREB1, NCOA1-3, and others." (PMID 39196362, 2024). "We found that under hypoxic tumor conditions, abundant VEGFA is released, generating 2 distinct tumor immuno-angiogenic ecosystems in male patients when stratified based on high or low ESR1 expression." (PMID 38411438, 2024). "To determine if tumor ER expression, both α (ESR1) and β (ESR2), plays a role in brain tumor protective function, we performed an analysis of gene expression in the GBM dataset." (PMID 38411438, 2024). "This intriguing result aligns with existing literature highlighting ESR1 expression in tumour cells and ESR2 expression primarily in normal tissue adjacent to the tumour site." (PMID 38832821, 2024). "ESR1 had an absolute R value greater than 0.5 in 5 tumor types (strong correlation), an R value ranging from 0.3 to 0.5 in 8 tumor types (moderate correlation), and an R value less than 0.3 in 6 tumor types (weak correlation)." (PMID 38666956, 2024). "We successfully discovered a positive correlation between the expected response to endocrine treatments with tumor ESR1 transcript abundance." (PMID 36574653, 2023). "We evaluated the anti-tumor activity of CB-103 with fulvestrant in ESR1-mutant (Y537S), endocrine-resistant BC xenografts." (PMID 37568775, 2023). "In addition, since acquired ESR1 amplifications in mBC specimens are a novel finding of our study, we also investigated whether specific types of ET are associated with the acquisition of ESR1 gene amplifications and/or the selection of tumor clones bearing ESR1 amplification." (PMID 36595552, 2023). "We then integrated Xenium and Visium data to derive differentially expressed genes from a tumor region containing cells expressing RNA of three receptors (ERBB2 + /ESR1 + /PGR+)." (PMID 38114474, 2023). "For instance, luminal cells with low ESR1/PGR/HER2 were enriched in the tumor zone, and luminal B cells (L5) were enriched in the interface zone." (PMID 37644609, 2023). "D-0502 is another orally bioavailable SERD with anti-tumor activity in PDX models, including those with ESR1 mutations." (PMID 37019913, 2023). "Combination of CB-103 and fulvestrant significantly reduced tumor volume in an ESR1-mutant, the endocrine-resistant BC model." (PMID 37568775, 2023).
tumor (continued). "the clinical benefit rate (CBR) for ARV-471 200 mg QD was 37.1%, and the CBR for evaluable patients with mutant ESR1 (n=19) was 47.4%, and substantial on-treatment reductions in mutant ESR1 circulating tumor DNA levels were observed." (PMID 37496997, 2023). "TNF (p = 0.0284), PPARG (p = 0.0379) and ESR1 (p = 0.0268) were significant in tumor staging in GC patients." (PMID 37171392, 2023). "Camizestrant is an oral SERD that showed tumor growth suppression in PDX models, including those with ESR1 mutations." (PMID 37019913, 2023). "Our study identified critical molecular mechanisms for epigenetic regulation of ESR1 in ERα‐positive BC cells and provided a potential target for BC treatment to prevent tumor metastasis." (PMID 37881785, 2023). "Specifically, the favorable prognosis of high-YAP1 tumor in incremental ESR1 expression supports the inhibitory role of YAP1 on ESR1 signaling." (PMID 37894401, 2023). "Accordingly, we analyzed the correlation of the RNA transcript levels between ER-α encoding gene ESR1, PR encoding gene PGR, and HER2 encoding gene ERBB2 in tumor samples of BC patients." (PMID 36902278, 2023). "Using a TNBC MDA-MB-231 xenograft model we found that the expression of ESR1 significantly increases in the tumours of stressed mice." (PMID 36347335, 2023). "The combination of CB-103 and fulvestrant showed significant tumor growth delay compared to the control group but the effect was comparable to the monotherapies, consistent with the fact that wild type ESR1 is fully sensitive to fulvestrant." (PMID 37568775, 2023). "Several retrospective and prospective studies have shown that genomic alterations in Estrogen-receptor one (ESR1) can be characterized not only in tissue samples but also by sequencing circulating tumor DNA (ctDNA) in liquid biopsy." (PMID 37675216, 2023). "The emergence of some driver gene mutations during treatments was detected by circulating tumor DNA analysis, revealing mutations in RB1 and to a larger extent in PIK3CA and the ERα gene ESR1 itself." (PMID 36869202, 2023). "Estrogen receptor 1 (ESR1) and a progesterone receptor (PGR) were reported to participate in lipid metabolism by encoding estrogen or steroid receptors to promote tumor progression." (PMID 36900015, 2023). "We discovered that PAFAH1B3, ZIC2, and ESR1 were significantly different in tumor and normal tissues, which is consistent with the findings of the bioinformatic analysis." (PMID 37957420, 2023). "Protein interaction network shows that epidermal growth factor receptor [EGRF] and estrogen receptor 1 [ESR1] are tumor drivers and drug targeting factors." (PMID 37542141, 2023). "After analyzing tissue and circulating tumor DNA samples, results showed five ESR1-specific fusions disrupting the LBD, thus resulting in the ligand-independent activity of the receptor." (PMID 37958343, 2023). "Activation of the androgen receptor, NOTCH, and ESR1 signaling affects several aspects of breast carcinogenesis, from tumor development to progression and metastatic outgrowth through genomic and non-genomic pathways." (PMID 37958677, 2023). "In Luminal A and Luminal B subtypes, the ESR1 methylation level in tumor tissue was significantly lower than in the matched normal tissues (Luminal A: p < 0.0001, Luminal B: p < 0.0001)." (PMID 37881785, 2023). "This was verified in vivo in MDA-MB-231 xenografts; the model verified the loss of methylation on ESR1 promoter, and subsequent increase in ESR1 expression in primary tumours in mice subjected to restraint stress." (PMID 36347335, 2023). "In 36% of the ERBB2 low CN metastatic samples, we observed a low expression of ESR1, even though their primary tumor was ER+ and as such, endocrine therapy was received." (PMID 37968696, 2023). "As the tumour suppressor array analysis showed a decrease in methylation of ESR1 promoter region in response to 20 days of cortisol treatment, we further investigated that loss of methylation of ESR1 in TNBC cells." (PMID 36347335, 2023).
tumor (continued). "EGFR and ESR1 are obtained from the intersection of tumor drivers and tumor targeting drug factors in the interaction network." (PMID 37542141, 2023). "Currently, this neoplasia is classified into distinct subtypes based on tumor staging/grading and the expression of the estrogen receptor (ESR1), progesterone receptor (PgR), human epidermal growth factor receptor 2 (HER2), and the proliferation marker Ki-67." (PMID 37958677, 2023). "ESR1/PGR expression, ER and PR IHC, and the Luminal index in the primary tumor were positively associated with rCR in all patients as well." (PMID 37794508, 2023). "All downregulated overlapped DEGs except ESR1 were significantly expressed in the normal uterine tissue compared to tumor tissue." (PMID 37373974, 2023). "The enhanced immune infiltration requires additional validation by TIL counting on ESR1 mutant tumor sections." (PMID 35440136, 2022). "Transcription of ESR1 gene is subjected to inhibitory autoregulation that was predicted to involve a network consisting of a multifunctional tumour suppressor gene DIRAS3, TGFB1, and transferrin receptor TFRC." (PMID 35218417, 2022). "We propose that de-repression of cell cycle genes as well as Esr1 promoter repression differ in HR + and HR- tumor models due to the change in Rbf status." (PMID 36333737, 2022). "Targeting the Hippo pathway by VT02956 represses ESR1 expression and inhibits the growth of ER+ breast cancer cells as well as patient-derived tumour organoids." (PMID 35217640, 2022). "A case study showed partial regression of tumor growth in a metastatic breast cancer patient with ESR1 amplification upon estrogen therapy." (PMID 35053443, 2022). "Detection of tumor type-specific alterations, including AR, ESR1, GNAS, and EGFR alterations in seven samples, as well as EBV, HBV, and MSI positivity in three samples, informed potential tumor origins." (PMID 35486650, 2022). "First, we modeled lncRNA expression as a multivariate function of ESR1 mRNA expression, fibroblast and lymphocyte infiltration scores reflecting fibroblast or lymphocyte tumor content." (PMID 35982125, 2022). "To further investigate the biological differences between early AI responders and resistant tumours we evaluated the ESR1 gene expression levels amongst the four intrinsic subtypes." (PMID 35985932, 2022). "To illustrate the essence of the tumor's classification on ESR1 in the context of the other two genes, we present heatmaps built for s.cutoff classification that improves the specificity." (PMID 36335194, 2022). "ESR1 is an estrogen receptor protein coding gene that is a biological indicator of tumor status in BC." (PMID 35804819, 2022). "There is increasing evidence that estrogen affects the proliferation and tumor progression of the prostate epithelium through the ESR1 signal." (PMID 35686089, 2022). "ESR1 has been identified as a tumor suppressor gene, with hypermethylation of the promoter correlated with tumor growth." (PMID 35628212, 2022). "An epigenetic study of HCC also confirmed ESR1 as a tumor suppressor gene, with up to 83% of HCC patient tumors demonstrating ESR1 promoter hypermethylation and predicting tumor progression." (PMID 34881186, 2021). "ESR1 and PGR transcription levels were correlated with the tumor stage (p < 0.05), and the higher expression of ESR1 and ESR2 are associated with higher tumor stage." (PMID 34322374, 2021). "In summary, we identified significant differences in the expression levels of ESR1, ESR2, and PGR mRNAs in different cancer types, which associated with tumor progression and clinical prognosis." (PMID 34322374, 2021).
tumor (continued). "Conversely, expression of Esr1 (p = 0.02) was significantly reduced in tumours collected at diestrus compared to estrus." (PMID 34174867, 2021). "Our results indicate a high discrepancy (>60%) in the ESR1/PR status between the primary tumor and EpCAM(+) CTCs, and that ER/PR are expressed at a very low percentage in CTCs in respect to paired primary tumors." (PMID 33799422, 2021). "In this study, the total concordance rate between ESR1 status on tumor tissue DNA and ctDNA was 91%." (PMID 33777770, 2021). "Specifically, uLM are associated with alterations of DNA methylation, increased mRNA expression of estrogen receptor 1 (ESR1;), and DNA methyltransferases in tumor samples compared to the normal myometrium." (PMID 34445194, 2021). "ESR1, ESR2, and PGR mRNAs were found to be differentially expressed in different cancer types, and were associated with tumor progression and clinical prognosis." (PMID 34322374, 2021). "In high-grade serous ovarian cancer patients, there was ERS1 methylation in primary tumors and paired circulating tumor DNA, and ESR1 methylation had a remarkable consistency between primary tumors and paired circulating tumor DNA." (PMID 33936202, 2021). "Our findings suggest that many of patients who had elevated expression of tumor‐specific signatures such as ESR1, AR, VEGF, AKT1/2/3, CCND1, CDK1, and MMP9 had significantly poorer disease‐free survivals compared with the remaining subgroups." (PMID 33275817, 2021). "The SNP rs2234693 in the ESR1 gene was genotyped on DNA from formalin-fixed paraffin embedded (FFPE) tumor tissue using Taqman assays and related to the primary endpoint disease-free survival (DFS) and secondary endpoint overall survival (OS)." (PMID 33547330, 2021). "Further investigation into the mechanism demonstrated that ESR1 acts as a tumor suppressor by inhibiting the JAK/STAT3 signaling pathway." (PMID 33865377, 2021). "We have shown that Esr1 is required for a female-specific liver gene expression pattern and protects female livers from carcinogen-induced tumor formation." (PMID 34068249, 2021). "ILC tumours show discordance between ESR1 mRNA levels and ERα and in fact have alternate ER signalling pathways." (PMID 33413533, 2021). "In the MBC population of the patients, one actionable mutation—PIK3CA, ESR1, ERBB2, or AKT1—was found in ten patients and two in three cases either in the tumor or in the plasma." (PMID 34298704, 2021). "Our findings on the combined effect of ICI and mTOR inhibitors on the SC31 model further support the case for estrogen-related effects on ESR1– cells in this tumor model." (PMID 34944995, 2021). "For female mice in the tumor study, the uterus was much smaller in Esr1 KO mice compared to WT and heterozygous littermates." (PMID 34068249, 2021). "According to dissection of molecular features using omics approaches and prediction analysis of microarray 50 (PAM50) analyses, SC31 (a luminal-A subtype), with high expression of ESR1 (encoding ERα) and BCL2, is an estrogen-stimulation-dependent tumor model." (PMID 34944995, 2021). "Prior research has shown that most of the resistant tumours remain ERα-positive and critically dependent on activity of this signalling axis, with activating ESR1 gene mutations occurring in 15–40% of advanced cancers." (PMID 34944934, 2021). "Gene expression in tumor-resistant Esr2 heterozygous females and Esr2 KO females also showed an overall normal WT female gene expression profile for Esr1-dependent genes." (PMID 34068249, 2021).